PGK1 (phosphoglycerate kinase 1)
Diseases named in the same sentence as PGK1 in open-access papers (continued):
Sharing a sentence is not in itself a finding about the gene and the disease.
amyotrophic lateral sclerosis (5 papers, 2019 to 2024). Amyotrophic lateral sclerosis (ALS) is a neurodegenerative disease characterized by progressive muscular paralysis reflecting degeneration of motor neurons in the primary motor cortex, corticospinal tracts, brainstem and spinal cord. "Terazosin was shown to increase PGK1 activity and glycolysis in motor neuron models of amyotrophic lateral sclerosis (ALS), which correlated with protection and survival." (PMID 36835598, 2023). "Then, we retrieved a clinical trial named Terazosin RepUrposing Study in amyotrophic lateral sclerosis: a pilot study targeting PGK1 with terazosin in ALS patients (ID: ISRCTN45028842) from ICTRP Search Portal (who.int)." (PMID 37723547, 2023). "Not only did supplementary Pgk1 enhance NOM in defective cells, but injection of Pgk1 rescued denervation in muscle-specific NogoA-overexpression of zebrafish and an Amyotrophic Lateral Sclerosis mouse model, SOD1 G93A." (PMID 31361595, 2019). "Indeed, intramuscular injection of Pgk1 was shown to significantly reduce or delay neuromuscular junction (NMJ) denervation in Rtn4al-overexpressing Amyotrophic lateral sclerosis (ALS)-like zebrafish and SOD1-mutated ALS-like mice, leading to improved muscle contraction and mobility." (PMID 39409082, 2024).
breast tumors (5 papers, 2007 to 2021). "CCNB2and PGK1 are the genes overexpressed in both PBMCs and breast tumors.Interestingly, as the two genes drive cancer progression, they can be used as BC signaturegenes." (PMID 34455715, 2021). "To investigate the effect of the miR-16-1-3p/PGK1 axis on breast tumor growth in vivo, we used MDA-MB-231 cells harboring anti-miR-16-1-3p or PGK1 shRNA or anti-miR-16-1-3p plus PGK1 shRNA to inject the mammary fat pads of BALB/c nude mice." (PMID 33344462, 2020). "Importantly, the anti-miR-16-1-3p’s stimulatory effect on breast tumor lung metastasis was abolished by PGK1 knockdown." (PMID 33344462, 2020). "Overexpression of the TPI, PGK1 and ENO1 enzymes has been demonstrated in a series of breast tumors." (PMID 28430808, 2017). "Three enzymes of the 187 gene profile, TPI, PGK1, and ENO1, which are involved in the glycolytic pathway, were also found to be significantly overexpressed in the HER-2/neu-positive breast tumors." (PMID 17989776, 2007).
Hypertension (5 papers, 2021 to 2025). The presence of chronic increased pressure in the systemic arterial system. "The survival status of patients with PTC was considered the dependent variable, and gender, age, history of hypertension and diabetes, metastasis, differentiation degree, TNM staging, tumor diameter, and PGK1 expression levels were considered single factors for univariate Cox regression analysis." (PMID 40771921, 2025).
melanoma (5 papers, 2005 to 2024). A malignant, usually aggressive tumor composed of atypical, neoplastic melanocytes. "PGK1, which was initially selected as housekeeping gene, showed indeed no differential expression in the melanoma cell lines." (PMID 15900300, 2005).
oral squamous cell carcinoma (5 papers, 2021 to 2025). "PGK1 has been linked to AKT phosphorylation in oral squamous cell carcinoma." (PMID 38163864, 2024). "Activation of PGK1 under hypoxic conditions promoted glycolysis and increased stem cell-like properties and the epithelial-mesenchymal transition in oral squamous cell carcinoma cells." (PMID 34869590, 2021). "In oral squamous cell carcinoma (OSCC), m6A modification of PGK1 mRNA can be facilitated by KIAA1429 and recognized by YTHDF1, resulting in increased stability of PGK1 mRNA." (PMID 41373022, 2025). "For example, high PGK1 expression resulted in the promotion of glycolysis, enhancing the stem cell-like properties and EMT by activating AKT signaling in oral squamous cell carcinoma cells." (PMID 35869254, 2022).
Sepsis (5 papers, 2017 to 2025). Sepsis is defined as life-threatening organ dysfunction caused by a dysregulated host response to infection. "Our results revealed a significant upregulation of PGK1 in sepsis patients, with the area under the ROC curve (AUC) exceeding 0.9 across multiple datasets, indicating PGK1’s strong potential as a diagnostic biomarker." (PMID 39712033, 2024). "The significant upregulation of PGK1 in sepsis patients and its association with immune-related pathways and cell types highlight its potential role in the pathogenesis of sepsis." (PMID 39712033, 2024). "This study concluded that PGK1 served as a novel diagnostic biomarker for sepsis, with potential implications for prognosis and immune regulation." (PMID 39712033, 2024). "In conclusion, our study demonstrated that PGK1 serves as a novel diagnostic biomarker for sepsis, with potential implications for prognosis and immune regulation." (PMID 39712033, 2024). "The expression of PGK1 was found to be closely associated with various immune-related pathways and immune cells, suggesting its involvement in the immune response to sepsis and provide novel insights into the underlying regulatory mechanisms of PGK1." (PMID 39712033, 2024). "We demonstrated a significant upregulation of PGK1 in sepsis patients, underscoring its diagnostic value." (PMID 39712033, 2024). "The high AUC values obtained from ROC curve analysis demonstrate the excellent diagnostic performance of PGK1 in distinguishing sepsis patients from healthy controls." (PMID 39712033, 2024). "In this study, we aimed to investigate the diagnostic potential of PGK1 in sepsis by examining its expression in patients with sepsis and evaluating its correlation with immune cell." (PMID 39712033, 2024). "We posited that PGK1 may serve as a sensitive and specific biomarker for the diagnostic assessment of sepsis, offering a novel perspective on the interplay between immunity and organ dysfunction in this complex clinical scenario." (PMID 39712033, 2024). "The consistent upregulation of PGK1 across multiple GEO datasets and validation by qPCR and western blotting analysis in our study highlights its potential as a diagnostic biomarker for sepsis." (PMID 39712033, 2024). "Our study’s finding of PGK1 upregulation in sepsis was consistent with these findings, indicating a broader role for PGK1 in immune system activation and disease progression." (PMID 39712033, 2024). "The role of PGK1 in promoting pro-inflammatory immune responses and inhibiting immune suppression in sepsis was consistent with its known function as a key enzyme in the glycolysis pathway." (PMID 39712033, 2024). "This study elucidated the potential role of PGK1 in the pathogenesis of sepsis through the integration of microarray and single-cell RNA sequencing data." (PMID 39712033, 2024). "The area under the ROC curve (AUC) of PGK1 to significantly distinguish between the normal group and the sepsis group was 0.950." (PMID 39712033, 2024). "FCGR3A+ monocytes, and CD14+ monocytes from the sepsis patients presented the highest PGK1 expression compared to the other patients and other cell types." (PMID 39712033, 2024). "The GSE65682 dataset was used to explore the correlation between PGK1 and the prognosis in sepsis, and the sepsis patients were divided into high PGK1 group and low PGK1 group according to the median value of PGK1." (PMID 39712033, 2024). "Sepsis patients with high PGK1 expression presented higher memory B cells, monocytes, resting memory CD4 T cell and lower regulatory T cells." (PMID 39712033, 2024). "Here, we also investigated the correlation of between PGK1 expression and various immune signatures including chemokines and cytokines in sepsis." (PMID 39712033, 2024). "This warrants further investigation to better evaluate the prognostic value of PGK1 in sepsis patients." (PMID 39712033, 2024).
Sepsis (continued). "Together, scRNA-seq analysis suggested the distinct PGK1 expression and immunomodulatory effects in various cell types of sepsis." (PMID 39712033, 2024). "We used multiple GEO datasets (GSE28750, GSE57065, GSE65682, GSE95233, and GSE154918) to explore the different expression of PGK1 between healthy people and sepsis patients." (PMID 39712033, 2024). "The results showed that compared to the healthy controls, the expression of PGK1 mRNA was obviously increased in sepsis cohort." (PMID 39712033, 2024). "We also observed that PGK1 protein showed an increased trend in sepsis patients compared to healthy controls." (PMID 39712033, 2024). "We will also carry out further experiments in the future to explore the mechanism of PGK1 and the therapeutic effect of PGK1 inhibitors in sepsis, so as to develop more promising targeted therapies of sepsis." (PMID 39712033, 2024). "The scRNA-seq data provided valuable insights into the expression of PGK1 in different cell types in sepsis." (PMID 39712033, 2024). "We also constructed the map of 22 immune cells in sepsis samples, and investigated the immune infiltration feature of high PGK1 group and low PGK1 group." (PMID 39712033, 2024). "Four microarray datasets and a high throughput sequencing dataset were acquired from GEO database to reveal the PGK1 expression in patients of sepsis." (PMID 39712033, 2024). "Further research is needed to fully understand the role of PGK1 in the pathogenesis of sepsis and to explore its therapeutic potential." (PMID 39712033, 2024). "TZ binds Pgk1 and activates its enzymatic activity, with previous studies revealing a potential for conferring neuroprotection in animal models of sepsis and stroke." (PMID 28426667, 2017). "Previous studies using FDA approved terazosin (TZ), which activates PGK1, revealed protective effects in both stroke and sepsis models, most likely due to enhanced stress resistance, in keeping with our findings from SMA models." (PMID 28426667, 2017). "Besides, PGK1 level in the NS_LS group was significantly increased compared with the S and NS_ES groups, suggesting that PGK1 can potentially be a predictive marker for survival of sepsis." (PMID 39712033, 2024). "The ability PGK1 to distinguish between sepsis and non-sepsis conditions could aid in earlier identification and treatment of sepsis." (PMID 39712033, 2024). "The relationship between PGK1 expression and a spectrum of inflammatory mediators, including chemokines and cytokines, further corroborates its involvement in the inflammatory response during sepsis." (PMID 39712033, 2024). "This correlation indicated that PGK1 may be involved in promoting pro-inflammatory immune responses, which were characteristic of the acute phase of sepsis." (PMID 39712033, 2024). "The association with leukocyte transendothelial migration, TNF signaling pathway and PI3K-Akt signaling pathway indicated that PGK1 may contribute to the dysregulated immune response observed in sepsis." (PMID 39712033, 2024). "Additionally, microarray and single-cell RNA sequencing data integration, including gene set enrichment analysis (GSEA), KEGG and GO functional enrichment analysis, immune infiltration analysis, and single-cell sequencing analysis, were performed to elucidate the role of PGK1 in sepsis." (PMID 39712033, 2024). "Moreover, we verified the elevated PGK1 mRNA levels in our sepsis patients by qPCR." (PMID 39712033, 2024). "Our study suggested that PGK1 may inhibit the activation of these cells, leading to a shift toward a more pro-inflammatory state, potentially exacerbating the inflammatory process in sepsis." (PMID 39712033, 2024). "Furthermore, the correlation between PGK1 expression and the infiltration of various immune cell types in sepsis suggested that PGK1 may be involved in the regulation of immune cell recruitment and activation during the acute phase of sepsis." (PMID 39712033, 2024). "However, the role of PGK1 in sepsis remains largely unexplored." (PMID 39712033, 2024).
Sepsis (continued). "CD38high C1 monocytes of the Sepsis group highly expressed oxidative stress related genes and glycolysis signature related genes, such as ENO1, PKM, PGK1, and LDHA, which were key glycolytic enzymes." (PMID 40145840, 2025). "However, the specific role of PGK1 in the dysregulated immune response in sepsis remains unclear." (PMID 39712033, 2024). "The enrichment of PGK1 in various immune functional pathways, as revealed by GSEA analysis, suggested its involvement in the immunopathology of sepsis." (PMID 39712033, 2024).
Alzheimer disease (4 papers, 2014 to 2025). A progressive, neurodegenerative disease characterized by loss of function and death of nerve cells in several areas of the brain leading to loss of cognitive function such as memory and language. "Although this study did not directly assess ATP5F1A acetylation levels, our proteomic analysis revealed significantly elevated lactylation levels of the mitochondrial metabolic enzyme phosphoglycerate kinase 1 (PGK1) in Alzheimer’s disease tissues." (PMID 40800583, 2025). "PGK-1 was described as being oxidized also in the frontal cortex of patients with Alzheimer’s disease (AD), and in transgenic mice with Alzheimer plaque pathology." (PMID 25470616, 2014).
cervical cancer (4 papers, 2021 to 2025). A primary or metastatic malignant neoplasm involving the cervix. "In cervical cancer, phosphoglycerate kinase 1 (PGK1) promotes tumor growth, and MIR210HG may promote PGK1 expression." (PMID 38706901, 2024).
esophageal cancer (4 papers, 2019 to 2025). A primary or metastatic malignant neoplasm involving the esophagus. "According to this study, PGK1 is abnormally overexpressed in esophageal squamous cell carcinoma, and in patients with esophageal cancer, its expression is highly associated with a poor prognosis." (PMID 40534132, 2025). "Performing immunohistochemistry analysis in 108 esophageal cancer tissues, we discovered that advanced esophageal cancer tissues (Stage III and IV) had noticeably greater levels of PGK1 expression than that in early phase esophageal cancer (Stage I‐II)." (PMID 40534132, 2025). "Survival analysis based on PGK1 expression data of 108 esophageal cancer patients in Zhongshan Hospital was performed." (PMID 40534132, 2025). "All of the esophageal cancer cells expressed more PGK1 than HET‐1A cells, according to the results of qRT‐PCR and Western blot." (PMID 40534132, 2025). "Collectively, the results suggested that hypoxia tumour microenvironment promotes cell proliferation, stemness and metastasis via transcriptionally regulating PGK1 expression in esophageal cancer." (PMID 40534132, 2025). "Esophageal cancer bioinformatics analysis and tissue microarray analysis were employed to elucidate the aberrant expression of PGK1 during ESCC progression." (PMID 40534132, 2025). "We investigated PGK1 expression in a batch of esophageal cancer cell lines and esophageal normal cells to clarify the role of PGK1 in esophageal cancer." (PMID 40534132, 2025). "According to the research, PGK1 expression was higher in esophageal cancer than in nearby non‐tumour tissue." (PMID 40534132, 2025). "To investigate the differential expression of PGK1 in esophageal cancer and non‐cancerous tissues, we first analysed the levels of PGK1 from databases." (PMID 40534132, 2025). "Gaining a better understanding of these mechanisms is essential for improving our knowledge of tumour biology and has great potential for guiding the creation of tailored treatments meant to stop hypoxia‐driven PGK1 upregulated esophageal cancer processes." (PMID 40534132, 2025). "Through experiments involving both the overexpression and silencing of PGK1, we elucidated its pivotal role in facilitating esophageal cancer progression, including tumour growth, metastasis, and maintenance of cancer stemness." (PMID 40534132, 2025). "Significantly, Elevated PGK1 was substantially linked to both advanced TNM stage in breast and esophageal cancers as well as short overall survival (OS) in cancers of the breast, liver, lung, stomach, and esophagus." (PMID 37821504, 2023). "At the same time, PGK1 also performed instability in esophageal cancer samples and all esophageal samples, and HPRT1 was also unstable in normal esophageal samples." (PMID 36467891, 2022). "Next, we assessed PGK1's predictive significance in esophageal cancer." (PMID 40534132, 2025). "These strong results imply that PGK1 may be a feasible therapeutic target in esophageal cancer and offer important insights into the molecular mechanisms driving tumour hypoxia." (PMID 40534132, 2025). "Furthermore, qRT‐PCR and immunoblotting assay in esophageal cancer tissues and paired peri‐tumour esophageal tissues demonstrated that PGK1 was significantly augmented in esophageal cancer tissues." (PMID 40534132, 2025). "Up to now, there have been no studies on the relationship between PGK1 and esophageal cancer, the precise roles and molecular mechanisms underlying its function in ESCC remain insufficiently elucidated." (PMID 40534132, 2025). "In this work, by analysing esophageal cancer specimen, PGK1 is highly expressed in esophageal cancer tissues across multiple cohorts and positively correlates with the size, invasion depth, lymph node metastasis, differentiation, TNM stage and poor prognosis, as a carcinogenic factor in ESCC." (PMID 40534132, 2025).
esophageal cancer (continued). "Positively correlated PGK1 S203 and PDHK1 T338 phosphorylation levels were significantly associated with short overall survival (OS) in cancers of the breast, liver, lung, stomach, and esophagus and with advanced TNM stage in breast and esophageal cancers." (PMID 31578148, 2019). "Immunohistochemistry staining for PGK1 and HIF‐1α protein was performed on consecutive sections of clinical samples from Stage I and Stage III esophageal cancer patients." (PMID 40534132, 2025). "In vitro, the results of western blot analysis showed that knockdown of MYH9 abrogated the alteration of the expression of β‐catenin/c‐Myc pathway biomarkers regulated by PGK1‐overexpression, and there was no obvious effect of PGK1 overexpression on MYH9 expression in esophageal cancer cells." (PMID 40534132, 2025).